MTOR (mechanistic target of rapamycin kinase)
Diseases named in the same sentence as MTOR in open-access papers (continued):
Sharing a sentence is not in itself a finding about the gene and the disease.
complication (1 paper, 2023). Any disease or disorder that occurs during the course of, or because of, another disease, treatment, or procedure. "The comprehensive regulatory effects of the mTOR pathway on the onset and development of diabetic bone complications render mTOR a potential therapeutic target." (PMID 37298150, 2023). "In preclinical investigations, the dominant state of mTOR (activation or suppression) and the interaction with other signaling pathways need to be further clarified to better understand the pathology of diabetic bone complications." (PMID 37298150, 2023).
COPA syndrome (1 paper, 2024). "Given that the disease mechanisms behind COPA syndrome skew T-cells toward the Th17 phenotype, mTOR inhibitors could be beneficial, with current evidence being scarce but promising." (PMID 39767180, 2024).
coronary atherosclerosis (1 paper, 2022). Atherosclerosis of the coronary vasculature. "Notably, a recent study revealed that the MALAT1/miR-15b-5p/MAPK1 and mTOR signaling pathways were essential to the development of coronary atherosclerosis." (PMID 35910856, 2022).
craniosynostosis (1 paper, 2022). Craniosynostosis is defined as the premature fusion of one or more cranial sutures leading to secondary distortion of skull shape resulting in skull deformities with a variable presentation. "Notably, craniosynostosis experimental studies have detected enhanced mTOR signalling in neural crest cells, which was associated with craniofacial bone lesions." (PMID 35285136, 2022). "More specifically, osteogenesis and craniosynostosis have both been correlated with mTOR signalling." (PMID 35285136, 2022). "Since PC1 has previously been shown to induce mTOR signalling and regulate mTOR pathway components activity, we proceeded to investigate the potential implication of PC1/PI3K/AKT/mTOR signalling network in craniosynostosis and its effect on the cell properties of primary cranial suture cells." (PMID 35285136, 2022).
cutaneous sarcoidosis (1 paper, 2024). "Efficacy and safety of mTOR inhibition in cutaneous sarcoidosis: a single-centre trial." (PMID 39382646, 2024).
cystadenoma (1 paper, 2020). A benign or borderline cystic epithelial neoplasm arising from the glandular epithelium. "Kidneys from Tsc1∆/∆ mice also exhibited multiple cystadenomas and increased immunostaining of phosphorylated ribosomal protein S6 (pS6) compared to Tsc1+/+ mice, consistent with constitutive mTOR activation following Tsc1 deletion." (PMID 32927859, 2020).
dry eye (1 paper, 2025).
ductal carcinoma in situ (1 paper, 2022). "Histological samples from the two patients affected by ductal carcinoma in situ were characterized by a negativity of almost all parameters analyzed, with the exception of a low expression of TGFβ (score 1+) in one patient and a low mTOR expression (score 1+) in another." (PMID 36556228, 2022).
dysferlinopathy (1 paper, 2023). "Analysis of muscle transcripts from patients with dysferlinopathy helped identify the following 7 upregulated DEGs involved in the cellular response to stress: HSPA9, RPTOR, MTOR, LAMTOR1, LAMTOR5, ATP6V0D1, and ATP6V0B." (PMID 38125829, 2023).
eccrine carcinoma (1 paper, 2012). An adenocarcinoma with eccrine differentiation arising from the sweat glands. "Additional investigation regarding the potential treatment of rare cases of apocrine-eccrine carcinomas with PI3K/Akt/mTOR pathway inhibitors, currently in clinical testing, may be of clinical interest." (PMID 23056620, 2012). "Based on our findings, targeted therapy including PI3K/Akt/mTOR pathway inhibitors, which is currently in clinical testing, may be potential treatment options for rare cases of apocrine-eccrine carcinomas." (PMID 23056620, 2012).
echovirus infection (1 paper, 2023). "We consistently showed that mTOR phosphorylation levels decreased after echovirus infection, suggesting that echovirus-induced autophagy is triggered by mTOR dephosphorylation." (PMID 37114059, 2023). "Our findings suggest that autophagy can be induced by echovirus infection via regulating mTOR/ULK1 signaling pathway and exhibits a proviral function, revealing the potential role of autophagy in echovirus infection." (PMID 37114059, 2023). "Therefore, further studies may be needed to elucidate the mechanism by which echovirus infection regulates mTOR/ULK1 signaling pathway." (PMID 37114059, 2023). "Furthermore, phosphorylated mTOR and ULK1 were both decreased upon echovirus infection." (PMID 37114059, 2023).
Ehrlich tumor (1 paper, 2021). "The treatment with the Fr-BuVt (200 mg/kg, 14 days) decreased the solid Ehrlich tumor volume and weight besides increased the expression of the pro-apoptotic proteins caspase-3 and BAX, but also decreased the expression of the proteins involved in proliferation NFκB, mTOR and ERK." (PMID 33413302, 2021).
endometrial disorder (1 paper, 2025). A non-neoplastic or neoplastic disorder that affects the endometrium. "Despite these advances, studies specifically evaluating the efficacy of mTOR inhibitors in tamoxifen-induced endometrial disorders remain limited." (PMID 39819881, 2025).
endometrioid tumor (1 paper, 2023). A benign, borderline, or malignant epithelial tumor of the female reproductive system characterized by the presence of glands and/or cysts lined by neoplastic cells that resemble endometrial cells. "Both endometrioid and non-endometrioid tumor histologies harbor mutations that upregulate the phosphoinositide-3 kinase/protein kinase B/mammalian target of rapamycin (PI3K/AKT/mTOR) pathway." (PMID 37839313, 2023).
essential thrombocythemia (1 paper, 2022). A chronic myeloproliferative neoplasm that involves primarily the megakaryocytic lineage. "In our previous work, activation of the mTOR pathway was most prominent in the bone marrow of primary myelofibrosis (PMF) and granulocytes of PMF and essential thrombocythemia patients." (PMID 35204748, 2022).
estrogen resistance (1 paper, 2016). "This is consistent with previous studies demonstrating that PI3K-Akt-mTOR pathway activity is inversely correlated with ER expression, can function as a compensatory pathway that drives anti-estrogen resistance, and is required for hormone independence." (PMID 27589846, 2016).
Ewing’s sarcoma family tumors (1 paper, 2013). "IMC-A12 was evaluated in combination with the mammalian target of rapamycin (mTOR) inhibitor temsirolimus in patients with refractory Ewing’s sarcoma family tumors." (PMID 23525758, 2013).
eye inflammation (1 paper, 2025). "Ongoing eye inflammation and antigen-dependent priming of T-cell receptors results in the phosphorylation of protein kinase B (PKB/Akt) and mammalian target of rapamycin (mTOR) in resting Tregs." (PMID 39839752, 2025).
fallopian tube carcinoma (1 paper, 2024). A carcinoma that arises from epithelial cells of the fallopian tube. "A report at the 2016 ASCO meeting showed a cohort of 379 patients with ovarian or fallopian tube carcinoma have been evaluated for 10 genes AKT1, AKT2, AKT3, mTOR, PIK3CA, PIK3C2B, PIK3R1, PTEN, TSC1, TSC2 in the PI3K/AKT/mTOR pathway." (PMID 38167649, 2024).
Familial adenomatous polyposis (1 paper, 2020). Familial adenomatous polyposis (FAP) is characterized by the development of hundreds to thousands of adenomas in the rectum and colon during the second decade of life. "Also, mRNA and protein levels of mTOR are increased in heterozygous mutant Apc∆716 mice, a model for human familial adenomatous polyposis (FAP), which is dependent on β-Catenin, suggesting a direct role of the WNT signaling pathway in mTOR regulation." (PMID 32455578, 2020).
familial cancers (1 paper, 2023). "It is also possible that this treatment could be applied to other types of cancers, including various familial cancers that are dependent on the insulin-regulated PI3K-Akt-mTOR pathway, and could represent the first effective prevention method that does not have adverse effects." (PMID 37679316, 2023).
female infertility (1 paper, 2017). Diminished or absent ability of a female to achieve conception. "In young mice, mTOR signaling is required for estrogen-mediated growth of endometrial cells, and dysregulated mTOR signaling leads to female infertility due to defects in ovarian, oviductal, and endometrial functions." (PMID 27980219, 2017).
Flavivirus Infections (1 paper, 2018). Infections with viruses of the genus FLAVIVIRUS, family FLAVIVIRIDAE. "Although the mechanistic principle of mTOR and Wnt signaling in neurodevelopment and response to flavivirus infection is well established, we suggest that host molecular innate control of such pathways could significantly impact CZS outcome explaining twins’ discordance." (PMID 29396410, 2018).
frontal lobe epilepsy (1 paper, 2020). A localization-related (focal) form of epilepsy characterized by seizures which arise in the frontal lobe. "Evidence also suggests that mutations in other regulatory proteins, such as the GATOR1 complex, can lead to disinhibition of the mTOR pathway, thus resulting in nocturnal frontal lobe epilepsy." (PMID 33192961, 2020).
Fulminant hepatic failure (1 paper, 2020). Hepatic failure refers to the inability of the liver to perform its normal synthetic and metabolic functions, which can result in coagulopathy and alteration in the mental status of a previously healthy individual. "The effects on molecular signaling pathways of AMPK, mTOR, P65, and STAT3 are also consistent with the previous researches, in which Plumbagin protects liver against fulminant hepatic failure and chronic liver fibrosis in LX-2 cells." (PMID 33456673, 2020).
gastric adenoma (1 paper, 2021). A neoplastic polyp that arises from the stomach. "Importantly, our experiments demonstrate not only that c-Myc can be a driver for gastric adenoma but also that the AKT/mTOR pathway could be the underlying mechanism of gastric tumorigenesis caused by c-Myc overexpression." (PMID 33259779, 2021). "By the establishment of a conditional transgenic mouse model, we show that gastric adenoma induced by c-Myc overexpression is achieved through activation of AKT/mTOR signaling." (PMID 33259779, 2021). "Importantly, our findings highlight a mechanism by which gastric adenoma can be induced by stomach-specific c-Myc overexpression through activation of the AKT/mammalian target of rapamycin (mTOR) pathway." (PMID 33259779, 2021).
gastric NETs (1 paper, 2017). "Aberrant mTOR signaling, through altered mTOR pathway component expression or activation, has been associated with prognosis in panNETs, SINET, gastric NETs, and SCLC." (PMID 28042953, 2017).
geographic atrophy (1 paper, 2018). "A small, phase I study of intravitreal sirolimus, another mTOR inhibitor, for geographic atrophy (GA) in AMD was halted early because two of the six patients developed rapid, progressive central retinal thinning on OCT." (PMID 30235234, 2018).
giant cell glioblastoma (1 paper, 2024). "In another patient with giant-cell glioblastoma and NF1 mutation, the use of everolimus (mTOR inhibitor) may have had an impact, but the patient died due to COVID-19 infection." (PMID 39684714, 2024).
giant cell tumor of bone (1 paper, 2020). "mTOR signaling pathway constitutes mTOR as a potential downstream signal activated in giant cell tumor of bone(GCTB)." (PMID 32351329, 2020).
Giardia infection (1 paper, 2023). "Collectively, we present the first attempt to link the occurrence of IEC autophagy with Giardia infection in vitro, and provides novel insights into the contribution of ROS-AMPK/mTOR-dependent autophagy to Giardia infection-related downregulation of TJ protein and NO levels." (PMID 36999034, 2023). "In conclusion, this study demonstrated that, in response to Giardia infection, IECs expressed a ROS-AMPK/mTOR-mediated autophagy machinery." (PMID 36999034, 2023).
glioneuronal tumors (1 paper, 2024). "Studies have indicated that the BRAF V600E mutation is also associated with the activation of the mTOR (mechanistic target of rapamycin) signaling pathway in glioneuronal tumors." (PMID 39201639, 2024).
glucocorticoid resistance (1 paper, 2015). "Glucocorticoid resistance was previously associated with a proliferative phenotype involving upregulation of glycolysis, cholesterol biosynthesis, and activation of PI3K/Akt/mTOR and Myc signaling pathways." (PMID 25869207, 2015).
Gorham syndrome (1 paper, 2023). "It has been confirmed that PI3K-Akt-mTOR plays a role in Gorham syndrome pathogenesis, which provides a theoretical basis for using sirolimus in the clinical treatment of Gorham syndrome." (PMID 37215116, 2023). "Gorham syndrome patients recovered completely using sirolimus (an mTOR inhibitor) to inhibit the RAS/PI3K/mTOR signaling pathway." (PMID 37215116, 2023).
gram-negative bacterial infections (1 paper, 2020). Infections caused by bacteria that show up as pink (negative) when treated by the gram-staining method. "Thus, the mechanisms underlying NLRP3 inflammasome, mTOR activity, and phagosome/lysosome in defense of Gram-negative bacterial infection still require clarification." (PMID 33117816, 2020).
growth deficiency (1 paper, 2018). "Moreover, it has been reported that both Akt-null and mTOR knockout mice exhibited significant skeletal muscle atrophy as well as growth deficiency, which also proved the essential role of Akt-mTOR pathway on muscle maintenance." (PMID 29615929, 2018).
hair diseases (1 paper, 2023). "This review examines the function of mTOR signaling in hair follicles and hair diseases, and talks about the underlying molecular mechanisms that mTOR signaling regulates." (PMID 37727765, 2023).
Heat Stroke (1 paper, 2022). A condition caused by the failure of body to dissipate heat in an excessively hot environment or during PHYSICAL EXERTION in a hot environment. "Therefore, it is not clear that whether exosomal miR-155 could be transferred from microglia to neuron in vivo and whether exosomal miR-155 could regulate mTOR signal pathway by targeting Rheb in heat stroke animal model." (PMID 35634460, 2022). "However, whether miR-155 could be transported from activated microglia to neurons through exosomes and then participate in the regulation of neuronal autophagy through mTOR signal pathway by targeting Rheb in heat stroke is still unknown." (PMID 35634460, 2022).
hemangioblastoma (1 paper, 2019). "The mTOR pathway is a potential target for VHL‐related hemangioblastomas." (PMID 31317677, 2019).
hemihyperplasia (1 paper, 2021). "In the first five consecutive patients, we examined genes involved in the PI3K/AKT/mTOR pathway, which is also known to cause syndromic hemihyperplasia, using tissue-blood paired high-depth exome sequencing." (PMID 34627330, 2021).
hemorrhagic stroke (1 paper, 2022). A stroke caused by a bleed on the brain. "mTOR/p70S6K signaling is an interesting target in hemorrhagic stroke that requires further investigation in subsequent research." (PMID 35211177, 2022). "The combined therapy increased the expression of synapse-associated proteins (SYP and PSD95), and the results suggest that the protective effects of the combined therapy on mTOR may be related to its ability to increase synaptic plasticity in the hemorrhagic stroke." (PMID 35211177, 2022).
hepatopathies (1 paper, 2018). "The pathways related to mTOR signaling in the pathogenesis of hepatopathies include the LKB1/AMPK/mTOR metabolic axis, PI3K/AKT/mTOR and Bcl-2/Bax-mediated apoptosis/autophagy, and ERK/mTOR-mediated autophagy, the AKT/mTOR/c-Myc axis, NF-κB/mTOR signaling and TSC/mTOR signaling." (PMID 30405406, 2018).
hereditary hemorrhagic telangiectasia (1 paper, 2022). A disorder of angiogenesis leading to arteriovenous dilatations: cutaneo-mucosal hemorrhagic telangiectasias and visceral shunting. "Hereditary hemorrhagic telangiectasias (HHT) and various slow-flow malformations (especially venous and lymphatic malformations) are caused by activating mutations of the AKT/mTOR pathway." (PMID 36293054, 2022).
hereditary neuropathy with liability to pressure palsies (1 paper, 2024). Hereditary neuropathy with liability to pressure palsies (HNPP) is an inherited peripheral nerve disorder characterized by recurrent mononeuropathy usually triggered by minor physical activities. "Genetic and pharmacologic targeting of the PTEN/PI3K/AKT/mTOR signaling pathway was used as a potential therapeutic strategy in the peripheral neuropathies Hereditary Neuropathy with Liability to Pressure Palsies (HNPP) and Charcot Marie Tooth disease type 1A (CMT1A)." (PMID 38383802, 2024).
hereditary sensory neuropathy type 1 (1 paper, 2022). "The SPT enzyme also regulates mTOR in cells from patients with hereditary sensory neuropathy type 1, a severe neurological disease caused by mutations in SPT encoding genes." (PMID 35691340, 2022).
hidradenocarcinoma (1 paper, 2015). A carcinoma with apocrine and less often eccrine differentiation, arising from the sweat glands. "Targeted therapy such as Akt/PI3K/mTOR pathway inhibitors, may have a role in hidradenocarcinomas but these are in clinical testing currently." (PMID 25815059, 2015). "The current focus for treatment of hidradenocarcinoma is on targeted therapies like trastuzumab, EGFR (epidermal growth factor receptor) inhibitors, PI3K/Akt/mTOR pathway inhibitors, hormonal agents like antiandrogens and electrochemotherapy but more future trials are required." (PMID 25815059, 2015).
Histiocytosis (1 paper, 2023). An excessive number of histiocytes (tissue macrophages). "Other signaling pathways for which we have specific inhibitors (AKT/mTOR, ALK, and CSF1R) now pave the way for targeted therapies rather than conventional chemotherapy regimens in adult clonal histiocytosis." (PMID 37809108, 2023).
hypercortisolemia (1 paper, 2022). "While there were no changes in the transcript abundance of brain insulin receptors, the reduction in the brain phosphorylation of Akt and mTOR points to a lower capacity for protein synthesis due to hypercortisolemia." (PMID 36127383, 2022). "Consequently, the reduced Akt-mTOR signalling in response to hypercortisolemia observed in the present study may reduce the protein synthetic capacity in the brain of fish." (PMID 36127383, 2022).
Hyperkalemia (1 paper, 2024). An abnormally increased potassium concentration in the blood. "Belatacept and mammalian target of rapamycin (mTOR) inhibitors offer an alternative to CNIs in the event of hyperkalemia; however, they should be prescribed to the appropriate patient." (PMID 38434606, 2024).
Hyperkeratosis (1 paper, 2024). Hyperkeratosis is a histopathological term defining a thickened stratum corneum and may be present in many different skin conditions, with many possible overlaps. "Another mouse model induced by PTEN deletion shows progression of epidermal hyperplasia, hypergranulosis, hyperkeratosis, mammary adenosquamous carcinoma, adenomyoepithelioma, and cutaneous SCC, accompanied by hyperactivation of mTOR and production of fibroblast growth factor (FGF)." (PMID 38564036, 2024).
hyperparathyroidism (1 paper, 2018). Hyperfunction of the parathyroid glands resulting in the overproduction of parathyroid hormone. "Hyperparathyroidism and secondaryhyperphosphatemia are being associated with LVH and probably involve similarpathways of mTOR activation." (PMID 29738042, 2018).